ENSG00000296025 (novel transcript)
Gene: Long non-coding RNA gene on chromosome 10 (7,485,416 to 7,492,725, forward strand). Ensembl gene ENSG00000296025.
Gene Ontology:
Molecular function: U4 snRNA binding
Biological process: formation of quadruple SL/U4/U5/U6 snRNP; spliceosomal tri-snRNP complex assembly
Cellular component: U4/U6 x U5 tri-snRNP complex; U6 snRNP